STAT1 (signal transducer and activator of transcription 1)
Diseases named in the same sentence as STAT1 in open-access papers (continued):
Sharing a sentence is not in itself a finding about the gene and the disease.
tumor (continued). "Correspondingly, compared with the BIN1-KO group, the BIN1-KO + sh-G3BP1 group exhibited a significantly reduced positive rate of G3BP1 expression in tumor tissues, whereas the positive rate of STAT1 expression was markedly increased." (PMID 40346580, 2025). "This suggests that the STAT1/serine metabolism pathway in tumor cells plays a role in inhibiting macrophage M2 polarization." (PMID 40368902, 2025). "Loss or downregulation of STAT1 is correlated with a poor prognosis, while induction of STAT3 activity also promotes the aggressiveness of the tumor." (PMID 40699751, 2025). "The further study found that the STAT1/STAT3 signaling pathway in tumor cells activated by IL-10 inhibited the PERK signaling pathway and alleviated the ER stress-mediated cell death in tumor cells caused by CAP treatment." (PMID 41145470, 2025). "Signal transducer and activator of transcription 1 inhibition or upadacitinib treatment mitigates inflammation and tumor development in Rbbp9-/- mice." (PMID 39631567, 2025). "This inhibition prolongs tyrosine phosphorylation of STAT1, a key signaling molecule in the IFN-γ pathway, thereby promoting tumor cell apoptosis in a STAT1-dependent manner." (PMID 41142809, 2025). "STAT1 was identified as an important target for vitcylation, with implications for interferon pathway activation and anti-tumor immunity." (PMID 40583064, 2025). "The activation of ISGs can either stimulate intrinsic cancer cell DDR response to IR via STAT1 pathway or foster tumor immune cell evasion resulting in immunosuppressive tumor microenvironment." (PMID 40646573, 2025). "Simultaneously, it inhibits IFN-γ-triggered PD-L1 upregulation in tumor cells through STAT1 acetylation, thereby reversing immunosuppression." (PMID 41251471, 2025). "Nevertheless, evidence from specific experimental and clinical studies suggests that STAT1 can display tumor-promoting activities under defined conditions." (PMID 40346580, 2025). "The IFN-γ/STAT1 pathway’s involvement in facilitating tumor progression has been previously discussed." (PMID 40909948, 2025). "Numerous studies have demonstrated that the activation of the IFN-γ/STAT1 pathway significantly improves the expression of several downstream factors, contributing to tumor cell proliferation and metastasis." (PMID 40909948, 2025). "IHC and multiplex immunofluorescence analyses demonstrated that STAT1 expression promoted CD8+ T-cell infiltration, suppressed M2 tumor-associated macrophages (M2-TAMs), and remodeled the immune microenvironment." (PMID 40849492, 2025). "The enzyme Indoleamine 2,3‐dioxygenase 1 (IDO1) is regulated by the interferon‐driven STAT1 axis and contributes to the balance of the tumor microenvironment (TME)." (PMID 40062505, 2025). "In this article, we describe that this mutation results in impaired nuclear import of tyrosine-phosphorylated STAT1 and induces tumor formation in older mice." (PMID 40287766, 2025). "Hematoxylin-eosin staining of the enlarged STAT1-∆N-expressing spleens demonstrated a markedly irregular pattern of tumor cells, exhibiting a thin rim of cytoplasm with small round nucleoli." (PMID 40287766, 2025). "The isolated tumor cells showed a constitutive hyperphosphorylation of the truncated STAT1 mutant, as well as STAT3, even before cytokine stimulation." (PMID 40287766, 2025). "Exogenous arachidonic acid enhances RSL3-mediated ferroptosis, while CAR-T cells engineered to secrete IFN-κ induce tumor ferroptosis via an IFNAR/STAT1/ACSL4 axis." (PMID 39849645, 2025). "Combination treatment with oHSV and Trametinib enhanced virus replication mediated by down-regulation of STAT1 and PKR expression or phosphorylation in BRAF V600E-mutated tumor cells as well as BRAF wt/KRAS-mutated tumor cells." (PMID 40248194, 2025). "The role of STAT1 is more controversial, in some studies it plays an oncogenic role, while others consider it as a tumor suppressor." (PMID 41463071, 2025).
tumor (continued). "We demonstrate that tumor-derived lactate facilitates the establishment of a self-sustaining positive feedback loop through activation of the H3K18la-STAT1-LDHA axis, thereby continuously amplifying lactate production and promoting tumor aggressiveness." (PMID 41208879, 2025). "Among them, STAT1 is involved in anti-tumor immune response, while STAT3 and STAT5 exhibit pro-tumorigenic properties, and their overexpression is closely associated with tumor progression and malignancy." (PMID 40364836, 2025). "Mass spectrometric analysis of tumours revealed that STAT1 (signal transducer and activator of transcription 1) is bound to RPS3." (PMID 40940922, 2025). "For example, STAT1 is an arbiter of interferon signaling, playing a critical role in antiviral defense and tumor suppression." (PMID 41115066, 2025). "IFN-γ activates STAT1 and STAT4, promoting Th1 differentiation, while inhibiting Th2 and Th17 differentiation, with the latter being linked to tumor progression." (PMID 39858472, 2025). "The majority of the STAT1-target genes examined showed significantly reduced transcriptional activity in tumor tissue compared to normal tissue." (PMID 40287766, 2025). "In contrast, STAT1 overexpression partially attenuated the tumor-promoting effects of G3BP1 overexpression and its suppression of CD8+ T cell infiltration." (PMID 40346580, 2025). "In our work, we observed nuclear localization of STAT1 in biopsies, as well as in tumor cells and HaCaT cells transduced with E6 and E7." (PMID 41367865, 2025). "Additional research indicates that STAT1 can act as both a tumor suppressor and an oncoprotein in cells with specific malignant phenotypes." (PMID 40407590, 2025). "Classically viewed as a tumor suppressor, activated STAT1 can induce expression of anti-tumor genes and enhance the cytotoxic functions of natural killer NK cells and T cells, thereby suppressing tumor growth and promoting apoptosis 24-26." (PMID 41208879, 2025). "The inferred activity of IRF1 and STAT1 regulons were positively correlated with the sum of normalized APPG expression in tumor cells (Pearson R = 0.78, p-value = 0)." (PMID 40894019, 2025). "Here, we demonstrate that the secretory autophagy of phosphorylated STAT1 and -2 (p-STAT1/2) in tumor cells elicits CXCL9hi macrophages, thereby enhancing CD8+ T cell–mediated antitumor immunity." (PMID 41321309, 2025). "Depletion of USP5 permits the transfer of p-STAT1/2 from tumor cells to macrophages in an LC3- and autophagy-dependent manner, conferring an immunostimulatory phenotype of macrophages." (PMID 41321309, 2025). "Cell viability assays indicated that the downregulation of STAT1 expression facilitated tumor cell proliferation." (PMID 40659662, 2025). "Even before cytokine stimulation, extracts from tumor cells demonstrated enhanced DNA-binding activity of STAT1-∆N to a high-affinity GAS site, confirming a basal activation level." (PMID 40287766, 2025). "Overall, the inhibition of FAT1 promoted tumor growth in vivo, whereas the overexpression of STAT1/IRF9 inhibited the tumor-promoting effect induced by FAT1 knockdown." (PMID 39781458, 2025). "IL‐10, secreted by tumor‐associated macrophages, stimulates cancer stem cell‐like characteristics in NSCLC cells via the JAK1/STAT1/NF‐κB/Notch1 pathway." (PMID 41223031, 2025). "The IFN-γ/STAT1 pathway not only activates downstream factors to exert antitumor effects but also directly interacts with other factors through STAT1 to inhibit tumor progression." (PMID 40909948, 2025). "Statistically, COX2 and p-STAT1 expression was significantly lower in HCC tumor tissues than in adjacent normal liver tissues, and nuclear pTyr-STAT3 expression was significantly higher in HCC tumor tissues than in adjacent normal liver tissues." (PMID 39826687, 2025). "STAT1 acts as a tumor suppressor or promoter depending on the cellular context and the type of cancer." (PMID 41439111, 2025).
tumor (continued). "The expression of the STAT1-ΔN variant resulted in the disruption of normal spleen architecture by malignant CD3- and CD20-negative tumor cells, which stained positively for both tyrosine-phosphorylated STAT1 and STAT3." (PMID 40287766, 2025). "To gain a better understanding of the anti-tumor mechanisms underlying combination therapy and the role of STAT1 in TCL, we transfected STAT1 shRNA into H9 and Karpas 299 cells, confirming effective STAT1 knockdown via qPCR and Western blot analysis." (PMID 40659662, 2025). "While other clinical studies and experimental results indicate that STAT1 has tumor-promoting properties." (PMID 40407590, 2025). "Tumor-associated macrophage-derived TGF-β1 induces nuclear translocation of PKM2 and promotes its interaction with STAT1, which activates the PD-L1 promoter and drives immune checkpoint expression." (PMID 40842995, 2025). "This study highlights the crucial role of the BIN1/G3BP1/STAT1/CD8+ tumor-infiltrating lymphocyte signaling pathway in the progression of NSCLC and its mechanisms of immune evasion." (PMID 40346580, 2025). "It was found that tumor cells C2_STAT1+ and apCAF (Fib_CD74+) would induce the exhaustion of cytotoxic T cells (CD8T_CNLY+), leading to enhanced resistance to tumor treatment." (PMID 40948762, 2025). "Studies have also demonstrated that HKDC1 enhances the expression of PD-L1 by binding with STAT1, thereby augmenting the immune escape capacity of tumor cells." (PMID 40406250, 2025). "Collectively, this establishes a tumor-derived lactate-driven positive feedback loop, defined herein as the “H3K18la-STAT1-LDHA” axis." (PMID 41208879, 2025). "Expression of STAT1 protects against invading microorganisms and triggers an immune response against transformed tumor cells." (PMID 40287766, 2025). "We detected a significantly higher density of CD68+Stat1+ macrophages within a 50 μm proximity to panCK+ tumor cells in responders compared to non‐responders (P<0.05)." (PMID 40995650, 2025). "The findings revealed that the ETV6-NTRK3 fusion gene precipitated a substantial activation of STAT1, both directly and indirectly, thereby inducing aberrant expression of downstream genes and facilitating tumor cell survival and invasiveness." (PMID 40584293, 2025). "A number of studies have revealed the tumor-suppressing properties of STAT1 in various cancer cells, which is consistent with the CRC data collected from the TCGA database and indicated better survival." (PMID 40406250, 2025). "Results showed that upon cytokine stimulation most of the studied genes were expressed at a lower level in the tumor cells than in control cells, such as Stat1, Irf1, Cxcl9, Cxcl10, IκBα, and Bcl2 (p< 0.05)." (PMID 40287766, 2025). "Subsequently, the phosphorylation level of STAT1/2 in the tumor tissues was detected by Western Blot." (PMID 40956299, 2025). "This creates a positive feedback loop wherein tumor-derived lactate promotes H3K18la modification, which subsequently elevates STAT1 and LDHA expression." (PMID 41208879, 2025). "Numerous investigations into gastrointestinal tumors have revealed that IRF-1 exhibits a ‘double-edged sword’ role, simultaneously promoting and inhibiting tumor progression by regulating various downstream factors mediated by the IFN-γ/STAT1 pathway." (PMID 40909948, 2025). "Future study ought to attempt to characterize the molecular mechanisms of STAT1 in tumor cells, as well as its role in the tumor microenvironment." (PMID 40659662, 2025). "We investigated the prevalence of those mutations before ICB by collating data from The Cancer Genome Atlas (TCGA) for pre-treatment tumours which harboured mutations in the IFNγ receptor subunits (IFNGR1/2) or downstream signalling molecules (JAK1/2, STAT1)." (PMID 39746898, 2025). "Since we observed an increase in pathways associated with inflammatory response, we further investigated tumor protein lysates for the activating phosphorylation sites Tyr701 and Ser727 of STAT1." (PMID 41429766, 2025).
tumor (continued). "Further, TMA-based IHC confirmed higher STAT1 expression in tumor tissues, correlating with increased tumor size and cervical lymph node metastasis." (PMID 41208879, 2025). "Several ISGs such as GBP family genes Gbp4 and Gbp5, Cxcl9, Oas2, and Stat1, were significantly downregulated in the old Tumor-3 subcluster." (PMID 41332581, 2025). "The combination of AR and JAK2/STAT1 inhibition resulted in a significant reduction in tumor growth, which was attributed to the diminished capacity for DNA damage repair and the increased propensity for apoptosis." (PMID 40001606, 2025). "In contrast to the tumor suppressor STAT1, which is a marker for favorable prognosis in different tumor types, the homologous STAT3 fulfills cell-autonomous functions in many cancer cells through maintaining stemcellness and promoting proliferation." (PMID 40287766, 2025). "Activated by interferons and interleukins, STAT1 plays a key role in antiviral defense, tumor suppression, and immune regulation, while exhibiting anti-proliferative and pro-apoptotic functions, promoting macrophage activation and chronic inflammation." (PMID 40775363, 2025). "In tumor-associated macrophages (TAMs), YTHDF2 is upregulated via the IL-10/STAT3 pathway and suppresses IFN-γ/STAT1 signaling, maintaining a pro-tumor phenotype." (PMID 41403953, 2025). "Conversely, chronic low-level IFN exposure can induce pro-tumor effects by fostering immunosuppression and resistance to RT and chemotherapy, and endogenous IFN/STAT1 activation has been associated with poor prognosis in proneural GBM." (PMID 39919036, 2025). "We also clarify potential mechanisms that operate for both EZH2 monotherapy and combination therapy in TCL, revealing the activation of STAT1 as one of the tumor-suppressive pathways contributing to the anti-tumor effects." (PMID 40659662, 2025). "IFNG and IFNGR1 are upstream regulators of STAT1, and the binding of IFNG to IFNGR1 activates STAT1, exerting anti-tumor effects." (PMID 40659662, 2025). "Frequently accepted regulators of neutrophil anti-tumor functions include STAT1 and IRF8, although their action is still context-dependent." (PMID 40050933, 2025). "Our data suggest that USP5 depletion in tumor cells drives LC3-related secretory autophagy of p-STAT1/2, resulting in intercellular transference of IFN-I signaling and macrophage activation." (PMID 41321309, 2025). "It promotes programmed death-ligand 1 (PD-L1) expression via the Janus Kinase/signal transducer and activator of transcription 1 (JAK–STAT1) pathway in both tumor and immune cells, contributing to immune evasion and reduced cytotoxic T cell activity." (PMID 40805243, 2025). "Here, we uncover the intercellular transfer of IFN-I signaling in the TME and demonstrate that tumor cell–intrinsic p-STAT1/2 is transferred to macrophages via secretory autophagy." (PMID 41321309, 2025). "Transcription factor signal transducer and activator of transcription 1 (STAT1) is recognized as a good prognostic factor in CRC known for its role in tumor immunosurveillance as well as apoptotic signaling, but its association with AF1q remains unexplored." (PMID 40062505, 2025). "The SRC‐1/STAT1/MMP12 axis promotes TAM polarization toward a pro‐tumor M2 phenotype, facilitates cancer cell proliferation, migration, and invasion, and ultimately accelerates PNI progression." (PMID 40985319, 2025). "Our findings reveal P4HA2 promotes CRC progression and suppresses anti-tumor immunity via STAT1/PD-L1 axis regulation." (PMID 40406250, 2025). "The following studies have demonstrated that activation of the IFN-γ/STAT1 pathway enhances the expression of various downstream factors, facilitating tumor cell escape from immune-mediated destruction and contributing to disease progression." (PMID 40909948, 2025). "And also, Stat1 is higher in post‐treatment tumor tissues from responders than those from non‐responders in PRJEB23709 and PRJEB25780." (PMID 40995650, 2025).
tumor (continued). "Collectively, these results demonstrate that arginine depletion promotes cooperative crosstalk between cancer cells, fibroblasts, and macrophages, driving STAT1 activation to support tumor survival." (PMID 41511309, 2025). "STAT2 deficiency in NPC cells abolished the increase in p-STAT1 and p-STAT2 in cocultured THP1-MΦ, implying the transfer of p-STATs from tumor cells to macrophages." (PMID 41321309, 2025). "Several in vivo pre-clinical models and CRISPR screens support this observation, as cell lines with mutations in IFNγR or downstream signalling molecules such as JAK1/2 and STAT1 have been shown to sensitise the tumour towards improved ICB response." (PMID 39746898, 2025). "STAT1 is a transcription factor that plays a pivotal role in regulating tumor progression and controls gene expression by activating the JAK-STAT signaling pathway." (PMID 40672756, 2025). "Activation of AP-1 and STAT1 eliminated purely pro-tumoral phenotypes and reduced anti-tumoral ones by 20%, shifting the tumor microenvironment toward elimination." (PMID 39827422, 2025). "Through RNA-seq analysis, we demonstrated that BIN1 knockout markedly suppresses STAT1 expression in tumor cells and tissues." (PMID 40346580, 2025). "STAT1, a key molecule of signal transduction in the tumor microenvironment, is closely related to the inflammatory response and tumor immune surveillance." (PMID 40406250, 2025). "The results revealed that either HCAR1 knockout or the addition of Endothall significantly increased the phosphorylation level of STAT1/2 in tumor tissues of mice." (PMID 40956299, 2025). "On the one hand, tumor cell C1_EGFR+ and C2_STAT1+ directly act on CD8T_GNLY+ through the MDK–(ITGA4+ITGB1) axis and the MIF–(CD74+CXCR4) axis to promote tumor proliferation." (PMID 40948762, 2025). "In silico analysis predicted stronger interaction for the rs2242780-C allele with STAT1/STAT3 proteins that regulate a range of biological functions related to immunity and tumor suppressor activity through the JAK/STAT pathway." (PMID 40646133, 2025). "have revealed that another type I family member IFN‐κ also drives tumour ferroptosis in combination with AA via the IFNAR/STAT1/ACSL4 axis." (PMID 40045458, 2025). "Higher IFN, STAT1, and iNOS signaling would indicate the macrophages have a higher capacity for orchestrating anti-tumor immunity." (PMID 41462606, 2025). "In cancer, ANRIL promotes tumor growth by repressing tumor suppressor genes and activating oncogenic pathways, including STAT1 and NF-κB." (PMID 40757146, 2025). "Unexpectedly, ETS1 also orchestrated an immune-cold tumor microenvironment by transcriptionally activating both STAT1 and PD-L1 (CD274) genes, suppressing T lymphocyte infiltration, and elevating immune checkpoint molecules." (PMID 40777467, 2025). "In conclusion, procaspase-1 and IRF-1 play crucial roles within the IFN-γ/STAT1 pathway, promoting the apoptotic death of tumor cells and thus providing viable targets for targeting malignancies." (PMID 40909948, 2025). "For example, after AEA activates CB2 receptors, it promotes tumor progression by inhibiting the JAK1/STAT1/3 signal of tumor-killing T cells and suppressing anti-tumor immunity." (PMID 41154659, 2025). "To elucidate the molecular mechanism by which circPIAS1 suppresses immunogenic ferroptosis by inhibiting STAT1 phosphorylation, we analyzed tumor tissues using IHC staining technique." (PMID 41347180, 2025). "The finding that STAT1 upregulates a few CRC-promoting genes is consistent with a growing number of recent observations that STAT1, in addition to its well-known tumor suppressor functions, can promote tumorigenesis, especially in solid tumors." (PMID 41226842, 2025). "The bulk of the evidence indicates that the activation of STAT1 exerts tumor-suppressive effects in cancer cells." (PMID 40346580, 2025).